BRCA2 (BRCA2 DNA repair associated)
Diseases named in the same sentence as BRCA2 in open-access papers (continued):
Sharing a sentence is not in itself a finding about the gene and the disease.
ovarian carcinoma (continued). "Women who have inherited the BRCA1 or the BRCA2 mutation are at greater risk of developing breast and/or ovarian cancer." (PMID 35096615, 2021). "Approximately 10–15% of epithelial ovarian cancer is caused by a germline mutation in the BRCA1 or BRCA2 gene." (PMID 34069790, 2021). "Consistently, BRCA2 mutated ovarian cancers with reduced PAXIP1 or CHD4 expression are associated with shorter progression-free survival and shorter overall survival." (PMID 34645978, 2021). "In recent years, inhibitors of poly(ADP-ribose) polymerase (PARP) have emerged as a promising new therapeutic approach for ovarian cancer treatment, especially for high-grade ovarian carcinoma with mutations in the BRCA1 or BRCA2 tumor suppressor genes." (PMID 34956861, 2021). "Firstly, BRCA1 pathogenic variants carry a higher lifetime risk of ovarian cancer occurring over a decade earlier than BRCA2-associated ovarian cancers." (PMID 34627117, 2021). "Similar to NF1, breast cancer 1 (BRCA1) and BRCA2 mutations are associated with an increased lifetime risk of developing cancer--particularly breast and ovarian carcinoma." (PMID 33954070, 2021). "•Patients with germ-line mutation in BRCA1 or BRCA2 have a significant increased risk of breast and ovarian cancer." (PMID 33996049, 2021). "To demonstrate the power of our approach, here we present a detailed analysis of an ovarian cancer patient, in which we describe constitutional somatic mosaicism of a BRCA2 mutation." (PMID 34068254, 2021). "Approximately, 10–15% of epithelial ovarian cancer (EOC) patients carry germline mutation in BRCA1 or BRCA2., and it was particularly high in high grade serous subtype, which was reported at about 20–30%." (PMID 33773534, 2021). "The mean age of ovarian cancer diagnosis of the 54 cases with BRCA1 or BRCA2 mutations was 57.5 years, which is higher than the mean age observed in other regions of Central Europe." (PMID 33478551, 2021). "BRCA1 and BRCA2 mutations were the most prevalent with the positive rate of 1.3% in the general cohort and 5.1% in breast or ovarian cancer patients." (PMID 35070997, 2021). "Whilst BRCA2 deficiency as a marker of platinum sensitivity has been well described in ovarian cancer cells, the data presented here provides evidence that FEN1 also has important roles in the repair of DNA damage induced by platinum agents." (PMID 33919707, 2021). "Founder mutations in BRCA1 (nine alleles) and BRCA2 (four alleles) are frequent among Polish breast and ovarian cancer patients." (PMID 33670479, 2021). "In contrast, women carrying a BRCA1 or BRCA2 pathogenic variant would consider delaying oophorectomy if found to have low ovarian cancer PRS assessment, as delaying the onset of surgically induced menopause was appealing." (PMID 34683136, 2021). "We then tested L82 cytotoxicity in PEO1 (BRCA2 deficient) and PEO4 (BRCA2 proficient) ovarian cancer cells." (PMID 34373746, 2021). "It is needed to further study and verify the role of BRCA1/BRCA2 reversion mutations in ovarian cancer." (PMID 33936202, 2021). "Especially as Poly (ADP-ribose) polymerase inhibitors have shown clinical benefit for treatment of breast or ovarian cancer with the presence of a BRCA1 or BRCA2 pathogenic variant, identifying these variants is more important than ever." (PMID 34063308, 2021). "Analogously, truncating BRCA2 mutations that lie within the Ovarian Cancer Cluster Region (OCCR) of exon 11 (nucleotides 3035-6629) have been correlated with significantly higher risk of OC." (PMID 34898566, 2021). "Here we have explored the effects of rucaparib, an inhibitor of PARP in the context of BRCA2 mutation in ovarian cancer cell lines in vitro." (PMID 34572083, 2021). "Taken together, the data provide preclinical evidence that FEN1 is a promising synthetic lethality target for BRCA2 deficient ovarian cancers." (PMID 33919707, 2021).
ovarian carcinoma (continued). "Patients with pathogenic sequence variants (PSVs) in BRCA1/BRCA2 are at high risk of developing ovarian cancer (OC)." (PMID 34930165, 2021). "BRCA1 and BRCA2 are two major high-penetrance breast/ovarian cancer predisposition genes, whose mutations can lead to high risk and early onset of breast and ovarian cancer." (PMID 34572941, 2021). "The BRCA1/BRCA2 reversion mutations in cfDNA were found by sequencing analysis from 21% of therapy-resistant of ovarian cancer patients." (PMID 33936202, 2021). "BRCA1 and BRCA2 genes alteration are also associate with other cancer types such as ovarian cancer (16.5–27%), prostate cancer (15%), pancreas cancer (2–7%) and possible melanoma." (PMID 34828379, 2021). "The different roles of BRCA1 and BRCA2 in genome protection confer distinct breast and ovarian cancer predisposition in mutation carriers." (PMID 34898566, 2021). "One of the four sgRNAs is associated with a single nucleotide variant in BRCA2 (c.-796C>T), which has been previously reported in patients with familiar breast and ovarian cancer, yet were classified as VUS in ClinVar." (PMID 33691754, 2021). "Our findings on APEX2 are supported by evidence that this ZNF protein serves as a synthetic lethal target in BRCA1- and BRCA2-deficient colonic and ovarian cancer cell lines." (PMID 33962398, 2021). "Mutations in the BRCA1 and BRCA2 genes are known risk factors and drivers of breast and ovarian cancers." (PMID 33525353, 2021). "Pathogenic variants in one BRCA2 allele confer higher risk of breast and/or ovarian cancers, as well as pancreatic and prostate cancers." (PMID 34356684, 2021). "Retention of the normal BRCA1 or BRCA2 allele is observed in 7% and 16% of BRCA1 and BRCA2 germline mutation-associated ovarian cancers, and it is associated with decreased overall survival in patients treated with platinum chemotherapy." (PMID 33922503, 2021). "Carriers of germline pathogenic variants (PVs) in BRCA1 or BRCA2 have a high lifetime risk of ovarian cancer, in particular high‐grade serous pathology." (PMID 33152107, 2021). "Delaying risk-reducing removal of ovaries and fallopian tubes until age 40–45 is reasonable for women carrying BRCA2 mutation (BRCA2m) because the average age of ovarian cancer onset is 8–10 years later than in BRCA1m." (PMID 34627117, 2021). "To date, the cellular origin and pathogenesis of OVCs are not well understood, but it was established that pathogenic germline mutations in BRCA1 or BRCA2 genes are the main risk factors in the development of ovarian cancer." (PMID 34207450, 2021). "Women with PVs in BRCA1 or BRCA2 have a cumulative lifetime risk of ovarian cancer of 44% to 61% and 17% to 24%, respectively." (PMID 33152107, 2021). "More recent evidence has shown that the risk of early-onset ovarian cancer is lower in BRCA2 PV carriers (0.4–4%)." (PMID 33926482, 2021). "Germline BRCA1 and BRCA2 mutations have been identified in 14–15% of all ovarian cancers while somatic BRCA1 and BRCA2 mutations are found in 6–7% of high grade serous EOCs." (PMID 33808562, 2021). "Compared to the normal population risk of about 1.4%, BRCA1 mutation carriers have an estimated 40% risk of developing ovarian cancer by age 70, while this risk is up to 18% for BRCA2 mutant individuals." (PMID 33435590, 2021). "BRCA1 mutation carriers are thus more likely to develop ovarian cancer than BRCA2 mutation carriers, as previously reported." (PMID 34680878, 2021). "Compelling evidence has shown that several interventions are effective in reducing the risk of future breast and ovarian cancer of women with BRCA1 or BRCA2 pathogenic variants." (PMID 34072979, 2021). "Overall, this study demonstrates considerable variation in transcriptomic landscapes of breast and ovarian cancers associated with the affected gene (BRCA1 vs. BRCA2), as well as the mutation type (somatic vs. germline)." (PMID 33525353, 2021).
ovarian carcinoma (continued). "We found that approximately 25.2% (54 patients) of unselected cases of ovarian cancer carried one of only six founder mutations in the BRCA1 or BRCA2 gene." (PMID 33478551, 2021). "Mutated germline alleles in the DNA damage repair (DDR) genes “breast cancer gene 1” (BRCA1) and BRCA2 have originally been identified as major susceptibility genes in breast and ovarian cancers." (PMID 34707985, 2021). "In a large study, LGRs were reported to constitute around 24% of BRCA1/BRCA2 PVs in high-risk breast/ovarian cancer families, while lower rates are reported in other series and in individuals without strong family histories." (PMID 34503154, 2021). "For this, we compared the relative viability of BRCA2-mutated ovarian cancer cell line PEO1 with that of BRCA2 WT revertant PEO4 cells upon WRN helicase inhibition." (PMID 34772932, 2021). "Women with pathogenic germline mutations in BRCA1 and BRCA2 genes have an increased risk to develop breast and ovarian cancer." (PMID 34552867, 2021). "Pre-clinically FEN1 blockade not only increased platinum sensitivity but was also synthetically lethal in BRCA2 and POLβ deficient ovarian cancer cells." (PMID 33919707, 2021). "Women with a BRCA1 or BRCA2 mutation are at an increased risk of developing hereditary breast and ovarian cancers." (PMID 33804884, 2021). "Patients with germ-line mutations in BRCA2 are predisposed to ovarian cancer development with a cumulative life time risk of about 20–30%." (PMID 33674744, 2021). "The present limitations in the pathogenicity prediction of BRCA1 and BRCA2 (BRCA1/2) missense variants constitute an important problem with negative consequences for the diagnosis of hereditary breast and ovarian cancer." (PMID 34207612, 2021). "Epithelial ovarian cancers are associated with a moderately strong genetic susceptibility, with heterozygous carriers of BRCA1 and BRCA2 germline mutations having increased lifetime risk of developing ovarian cancer of 40–60% and 11–30%, respectively." (PMID 34070674, 2021). "This phenomenon is well documented in the cases of recurrent chemoresistant ovarian cancer which has been shown to reacquire DNA repair proficiency by reversion of BRCA1/BRCA2 mutations or modification of epigenetic marks." (PMID 34283069, 2021). "The impact of germline mutations of BRCA1 and BRCA2 in breast and ovarian cancer are now well defined." (PMID 34830851, 2021). "We also discuss the impact of BRCA2 variants identified in patients with breast and/or ovarian cancers, which are detected throughout the whole BRCA2 protein, including the IDRs." (PMID 34356684, 2021). "By contrast, 39–44% of women who inherit a pathogenic BRCA1 variant and 11–17% of women who inherit the pathogenic BRCA2 variant will develop ovarian cancer by 70–80 years of age." (PMID 34207450, 2021). "Mutations in the tumour suppressor gene BRCA2 are associated with predisposition to breast and ovarian cancers." (PMID 34593815, 2021). "Similar to other studies, we also observed BRCA1 mutations occurring more frequently than BRCA2 mutations in Chinese ovarian cancer patients." (PMID 35070965, 2021). "Transcriptomic landscapes of breast and ovarian cancers show considerable variation depending on the affected gene (BRCA1 or BRCA2) as well as the mutation type (somatic or germline)." (PMID 33525353, 2021). "Over the past decades, a number of mutations have been identified in hereditary breast cancer, among which BRCA1 and BRCA2 mutations are the most prevalent and associated with increased risk of breast and ovarian cancer." (PMID 34439348, 2021). "BRCA1/BRCA2—both related to the homologous repair of DNA double-strand breaks—are the major breast/ovarian cancer susceptibility genes." (PMID 34287479, 2021). "According to investigations, several genes are associated with the pathogenesis of ovarian cancer, and amongst them, two genes—BRCA1 and BRCA2—are well-known ones and found to have significant associations with ovarian cancer." (PMID 33937409, 2021).
ovarian carcinoma (continued). "BRCA1 mutations are almost exclusively associated with female breast and ovarian cancer, whereas BRCA2 families are also at risk for male breast cancer, pancreatic cancer in both males and females, and prostate cancers." (PMID 33922503, 2021). "This is similar to previous reports on the association of BRCA2 mutations with increased response to cisplatin in ovarian cancer." (PMID 34065218, 2021). "BRCA2 germline mutations can predispose to ovarian cancer development with a cumulative lifetime risk of about 20–30%." (PMID 33919707, 2021). "In our study, we have screened 24 Pakistani cases for germline mutations causative for breast and ovarian cancer subtypes by doing targeted sequencing of BRCA1/BRCA2 genes, with moderate family history provided." (PMID 33773534, 2021). "At present, the only proven way to minimise the risk of ovarian cancer in the carriers of pathogenic variants in BRCA1/BRCA2 is prophylactic bilateral salpingo-oophorectomy." (PMID 34771713, 2021). "The most profound differences in ovarian cancers were observed between the transcriptomes of germline and somatic BRCA2 mutated cases." (PMID 33525353, 2021). "The prevalence and penetrance of deleterious variants in BRCA1 and BRCA2 has been extensively studied in ovarian cancer patients." (PMID 33086730, 2020). "Classification of variants in the BRCA1 and BRCA2 genes has a major impact on the clinical management of subjects at high risk for breast and ovarian cancer." (PMID 32814805, 2020). "DNA variants in a number of cancer susceptibility genes are known to be associated with ovarian cancer: women with a high penetrance genetic variant, such as a BRCA1 or BRCA2 mutation, are considered to be at high risk for developing breast and ovarian cancer." (PMID 33260928, 2020). "Our fifth BRCA2 pathogenic variant is c.7235_7236insG (p.Lys2413fs) it was detected in a patient with ovarian cancer." (PMID 32778078, 2020). "BRCA2 mutations in ovarian cancer are indeed so rare in several countries (0.9 - 2.5%) like Finland, Pakistan, India, and Denmark." (PMID 32856862, 2020). "An individual carried a pathogenic variant in PMS2 (NM_000535.6) implicated in Lynch syndrome and the two patients carried each a variant in BRCA1 (NM_007300.3) or BRCA2 (NM_000059.3), associated with hereditary breast and ovarian cancer." (PMID 32231684, 2020). "For tumors that harbor a known alteration in HRR genes, such as BRCA1 or BRCA2, higher tumor mutational burden and a greater number of tumor-infiltrating lymphocytes has been seen in breast and ovarian cancer." (PMID 32457830, 2020). "She had initially undergone genetic testing because of her strong family history of breast and ovarian cancers and was told that she had a pathogenic BRCA2 mutation." (PMID 32329193, 2020). "This is clinically relevant as heterozygous mutations in BRCA2 lead to haploinsufficiency in BRCA2 mutation‐carrying, breast and ovarian cancer patients." (PMID 32638521, 2020). "Ovarian cancer with BRCA1 or BRCA2 mutations had increased immune infiltrates compared to those without mutations." (PMID 33282564, 2020). "There were 23 patients with the BRCA1 mutation and 20 patients with the BRCA2 mutation out the 436 ovarian cancer patients sampled." (PMID 33282564, 2020). "The roles of BRCA1 and BRCA2 mutations in chemosensitizing ovarian cancer and improving prognosis are well known, as are the mechanisms by which these can be reversed in development of chemoresistance." (PMID 36046263, 2020). "Pathogenic variants in the BRCA1 and BRCA2 genes are linked to an increased risk for female breast and ovarian cancer (including early-onset breast cancer), male breast cancer, prostate cancer, pancreatic cancer, and certain other cancers." (PMID 32376921, 2020). "RAD52 is another therapeutic target in breast and ovarian cancer because its depletion is synthetically lethal to cells BRCA2 or BRCA1/PALB2 deficient." (PMID 32932697, 2020).
ovarian carcinoma (continued). "In particular, it is estimated to be 3% for carriers of mutations in BRCA1 and 5% to 10% for carriers of mutations in BRCA2, certainly lower than the risk of developing breast or ovarian cancer." (PMID 33198203, 2020). "A genome study of ovarian cancer recently revealed that BRCA1 and BRCA2 deficiency, either of which is considered the most important risk factor for hereditary BC and ovarian cancer, lead to different structural changes and mutation patterns in tumor genomes." (PMID 32719318, 2020). "In these studies, the frequency of germline pathogenic variants in BRCA1 in ovarian cancer cases were 5.1%, 3.6%, 3.7%, and 8.6%, respectively, and 3.9%, 3.3%, 4.0%, and 4.5% in BRCA2." (PMID 33086730, 2020). "Detection of mutations in the BRCA1 and BRCA2 genes from ovarian cancer is meaningful for both genetic counseling and treatment decision making with PARP inhibitors." (PMID 32856862, 2020). "Since 2014, indications of poly ADP ribose polymerase (PARP) inhibitors became available for ovarian cancer patients with germline or somatic mutations in BRCA1and BRCA2 genes." (PMID 32856862, 2020). "Signature 3 is also associated with germline and somatic BRCA1 and BRCA2 mutations in breast, pancreatic, and ovarian cancers." (PMID 32984050, 2020). "Women with a BRCA1 or BRCA2 mutation have high lifetime risks of developing breast and ovarian cancers." (PMID 32393849, 2020). "BRCA1 and BRCA2 are high penetrance genes associated with an increased risk of up to 20-fold for breast and ovarian cancer." (PMID 32039725, 2020). "The most significant risk factors for ovarian cancer are inherited genetic mutations of BRCA1 or BRCA2 genes that are responsible for about 10 to 15 percent of all ovarian cancers." (PMID 32823855, 2020). "In BRCA2, one of the splicing variants BRCA2-Δ3, has been shown to be associated with a high risk of developing breast or ovarian cancer." (PMID 32793288, 2020). "Most of the breast and ovarian cancer cases in Icelandic families have this BRCA2 founder mutation, while mutations in BRCA1 are very rare." (PMID 33086730, 2020). "Mutation in several genes in the pathway can result in HR deficiency; one of these is BRCA2, mutation of which increases ovarian cancer cell sensitivity to platinum‐based therapy." (PMID 32652647, 2020). "Deleterious mutations in the tumour suppressor genes BRCA1 and BRCA2 are associated with high risks of breast and ovarian cancer, and have been implicated in the genetic susceptibility to prostate cancer (PCa)." (PMID 31495749, 2020). "For example, breast and ovarian cancers frequently possess mutations of BRCA1 or BRCA2, which are vital genes of homologous recombination (HR), and these cancers often show the mutation signature with a distinctive pattern of substitutions and deletions." (PMID 33299637, 2020). "For BRCA1 mutation carriers, there is a predominant predisposition of breast and ovarian cancer, while BRCA2 mutation carriers also show a significantly higher risk of pancreatic, prostate, and other types of cancers in addition to breast and ovarian cancers." (PMID 33299637, 2020). "Because BRCA1 and BRCA2 account for ~25% of the familial breast and ovarian cancers, this section describes other breast and ovarian cancer predisposition genes." (PMID 32269964, 2020). "For example, previous studies reported that the BRCA1 and BRCA2 genes, which are associated with increased risk of ovarian cancer, harbor mutations associated with platinum drug sensitivity and survival." (PMID 32404140, 2020). "BRCA2 is crucial for repairing DNA double-strand breaks with high fidelity, and loss of BRCA2 increases the risks of developing breast and ovarian cancers." (PMID 32980867, 2020). "As new treatment options are developed to reduce the risk of breast and ovarian cancer in women who carry the BRCA1 or BRCA2 genetic mutation, it will become increasingly important to understand women’s preferences for risk-reducing treatment." (PMID 33014209, 2020).